IL10 (interleukin 10)
Diseases named in the same sentence as IL10 in open-access papers (continued):
Sharing a sentence is not in itself a finding about the gene and the disease.
cancer (continued). "The combination of adjuvant and blockade of IL-10 or T reg cell function might prove a successful strategy for improving cancer vaccines." (PMID 21533081, 2011). "Autologous serum is a possibility but the serum of cancer patients might contain high levels of inhibitory cytokines such as IL-6 or IL-10 that could affect DC function." (PMID 22082029, 2011). "Additionally, increasing evidence suggests a role for IL-10 in inhibition of angiogenesis, therefore decreases IL-10 expression would de-repress angiogenic activity and promote cancer progression." (PMID 20735825, 2010). "Numerous studies have shown that IL-10 may be involved in the pathogenesis of cancer, but the results were inconsistent." (PMID 20553628, 2010). "The impact of IL-10 on macrophage function appears to influence blood vessel growth, as reports indicate that IL-10 may contribute to the regulation of angiogenesis in various cancers." (PMID 20735825, 2010). "Reduced migratory capacity, inhibitedIL-12 cytokine production, inadequate Th1 and CD8+ T-cell response, and presumed generationof IL-10-producing tolerogenic DC could influence the outcome of DC-based vaccinationtherapies against cancer." (PMID 19009040, 2008). "It is postulated that IL-10 production in malignant tumors may facilitate their escape from immune surveillance." (PMID 15450122, 2004). "Reductions in IL-10 are noteworthy and warrant attention given that IL-10 is recognized as a key anti-inflammatory cytokine, as it promotes homeostasis (resolution of inflammation) and immune surveillance (preparation for robust response given need, e.g. cancer cells or pathogens)." (PMID 40778880, 2025). "The increased levels of IL-10 and IL-17 could provide additional benefits in cancer therapy." (PMID 40124384, 2025). "Additionally, cancer cells secrete immunosuppressive cytokines, such as IL-10 and TGF-β, which inhibit the effector functions of T lymphocytes and support the development of a population of regulatory lymphocytes (Tregs), which play a key role in suppressing the antitumor response." (PMID 40362280, 2025). "Next, we grouped them into cytokines associated with pre-cancer or the initiation stage of HCC (IL-6, TGF-β, MCP-1, FGF2, IL-2, IL-8, IL-12p40, IL-12p70, IL-18, IP-10, TNF-α, and IFN-γ), the early stage of HCC (OPN, GDF-15, RANTES, and VEGFA), and the advanced stage of HCC (IL-10, and MIP-3)." (PMID 41219858, 2025). "IL-10, an anti-inflammatory cytokine, may play a complex role in cancer progression." (PMID 40227503, 2025). "Interestingly, the observed strong inter-cytokine correlations, particularly between TNF-α and IL-10, in both cancer types may reflect a conserved immunoregulatory axis, but this interpretation should be viewed as exploratory." (PMID 41020868, 2025). "Moreover, it was confirmed that MSCs recruited from human cancers can actively increase the expression of immunosuppressive agents, i.e., IL-10, TGF-β1 and indoleamine 2,3-dioxygenase (IDO), and angiogenic factors, i.e., TGF-β1, VEGF, angiopoetin-1, endothelin-1, and IL-6." (PMID 39120301, 2024). "We propose that IL-10 may play different roles at various stages of cancer development." (PMID 39496002, 2024). "Therefore, we hypothesized that MEIS2 affected cancer cell growth through regulating the expression of IL10." (PMID 38711262, 2024). "Studies have shown that interleukin-10, along with other interleukins such as IL-1 and IL-4, can activate pathways like NF-κB, contributing to cancer radioresistance; therefore, strategies to inhibit IL-10 or its signalling pathways could enhance the efficacy of radiation therapy." (PMID 39682192, 2024). "Also, epigenetic regulation of IL-10 in cancer via ncRNAs is quite complex." (PMID 38186186, 2024). "Modulating the function of IL-10+ B cells by targeting sIgM in tissue sites could provide future avenues to treat a wide range of diseases in which IL-10+ B cells play an important role, ranging from inflammation to chronic infection and cancer." (PMID 38182585, 2024).
cancer (continued). "Although both IL-1 and IL-10 have the ability to promote cancer cell growth and support angiogenesis, leading to pro-cancer effects, it is worth noting that increased expression of IL-10 has been linked to the development of cancer and a negative prognosis in different types tumors." (PMID 38806619, 2024). "The decrease in their proliferation potential may be attributed to the secretion of several inflammatory molecules, such as IL-1β, IL-6, IL-8, IL-10, and matrix metallo-proteinases (MMPs) by cancer cells, which have adverse effects on the neighboring cells in the niche." (PMID 39768220, 2024). "Encouraging regular exercise could complement other cancer prevention measures, and insights into IL-10 signaling pathways may guide the development of exercise-based interventions or pharmacological agents that emulate the immune-modulating benefits of physical activity." (PMID 39769247, 2024). "Therefore, the specific function of IL-10 in cancer should be explored in further experiments." (PMID 38459564, 2024). "Our study revealed that elevated serum IL-6, TNF-α, and TGF-β and decreased IL-10 levels revealed that patients with ESCC and model mice demonstrated increased immune levels, and these inflammatory cytokines are considered important mediators associated with inflammation and cancer." (PMID 38834834, 2024). "Since IL-10 function represents an unresolved enigma in cancer therapy, and since circRNAs also have dual roles in cancer therapy, the comprehensive understanding of circRNAs regulating IL-10 expression and function might be the key to answering numerous questions." (PMID 38186186, 2024). "The anticancer potential of curcumin is observed in multiple cancer types, such as breast cancer and OSCC, and is associated with the suppression of the activity of Tregs and TAMs, as well as the downregulation of TGF-β and IL-10 by the MAO-A/STAT6 signaling pathway." (PMID 39605905, 2024). "In light of the wide spectrum of anti-inflammatory properties, IL-10 plays an important role in a variety of microbial infections and possesses potential therapeutic effects against several autoimmune diseases and even cancer (reviewed in references 8, to, 10)." (PMID 36541788, 2023). "However, studies have shown that B cells can sustain immune tolerance and inhibit autoimmune and inflammatory immune responses, as well as suppress immune surveillance responses during cancer by releasing anti-inflammatory mediators (e.g., IL-10) and inhibitory molecules (e.g., PD-L1)." (PMID 37519793, 2023). "In this study, we evaluated whether immune cells (CD4+ and CD8+ T cells) and immunosuppressive markers (PD-L1, CTLA-4, and IL-10) were present in peripheral blood and cancer tissues from GC patients, then investigated whether those findings were correlated with each other." (PMID 37153541, 2023). "However, the significance of IL-10 in cancer etiology and development is complicated." (PMID 38096329, 2023). "High or low levels of anti-inflammatory cytokines, such as interleukin-10, in the absence or presence of proinflammatory cytokines, such as interleukin-17, delineate the fate of T cells (regulatory T or T-helper 17 cells), which subsequently affect the progression of cancer." (PMID 37360782, 2023). "Therefore, it is reasonable to suggest that carnosine may exhibit anti-cancer activity in U937 cells by producing elevated levels of IL-10." (PMID 37998326, 2023). "In addition to the 84 shared DEGs, many of the DEGs that were unique to either the DOG2 or TARGET datasets were enriched for the same IPA pathways including PD-1 - PD-L1 cancer immunotherapy pathway, the IL-10 signaling pathway, and IL-12 signaling and production in macrophages." (PMID 37591946, 2023).
cancer (continued). "As reported, M1 macrophages hinder cancer progression via producing pro-inflammatory mediators (tumor necrosis factor-alpha and interleukin-1), while M2 macrophages advance cancer progression by means of anti-inflammatory cytokine secretion (chemokine 17, chemokine 22, and interleukin-10)." (PMID 37160813, 2023). "Therefore, a targeted approach against IL-10 with existing gene-therapy tools could provide a more effective cancer immunomodulatory strategy." (PMID 37454231, 2023). "In addition to its involvement in CV diseases, IL-10 could also serve as a biomarker for prognostic diseases or as a treatment target when taking into consideration the elevated concentration in cancer patients versus the healthy ones." (PMID 36830690, 2023). "TANs provide a favorable environment for cancer development, angiogenesis and metastatic spread by secreting cytokines and chemokines, such as interleukin-2 (IL-2), interleukin-6 (IL-6), interleukin-10 (IL-10), tumor necrosis factor α (TNF-α) and vascular endothelial growth factor (VEGF)." (PMID 36661728, 2023). "As mentioned, IL-10 might play different roles in various cancers." (PMID 38102207, 2023). "Therefore, IL-10 antagonists may be a critical factor that influences the success of cancer treatments." (PMID 38102207, 2023). "It indicates that IL10 may play a dual regulatory role in cancer." (PMID 35909123, 2022). "Therefore, the PC-3-medium-induced upregulation of IL-10 and IL-8 in TAMs may be attributed to microRNA(s) in cancer cells, promoting EMT in the TME." (PMID 35955737, 2022). "Besides broadening understanding of responses to herpesviruses, our results raise the possibility that reactivation of varicella-zoster may be counterproductive in cancer treatment through the action of IL-10-producing T-cells." (PMID 36314824, 2022). "In summary, macrophages could induce the activation of DLL3-dependent Notch1/Notch2 signaling, the upregulation of IL-33, and the degradation LG3BP and HSPA8, resulting in enhanced cancer-cell proliferation and elevated IL-1β, IL-12, and IL-10 secretion by macrophages." (PMID 35382168, 2022). "Thus, IL-10 can prevent cancer growth and metastasis by inhibiting M2 macrophages." (PMID 36289759, 2022). "Taken together, we speculated that the lower cytotoxic activity against cancer cells by HKTB-treated TEMs compared to HKTB-treated Ms might be a result of concomitant regulation between the high IL-10 and TGF-β levels and limited activation of inflammatory signaling." (PMID 35477732, 2022). "We also found that AP3S1 expression significantly and positively correlated with TGFB1 and IL-10 expression in pan-cancer, which in turn were significantly correlated with TAMs/CAFs, and we speculate that this may be a potential mechanism by which AP3S1 affects infiltration of TAMs/CAFs." (PMID 35874816, 2022). "Furthermore, some components existing in the tumor microenvironment were also found to directly reduce the immune response against cancer, including prostaglandin E2, vascular endothelial growth factor, interleukin IL-10 secreted from cancer cells, and transforming growth factor-β (TGF-β)." (PMID 36297426, 2022). "Besides, IL-10 induces cancer cell proliferation and metastasis through immunosuppression." (PMID 36437782, 2022). "In addition, direct inhibition of the immune mechanism occurs due to vascular endothelial growth factor, prostaglandin E2, transforming growth factor-β (TGF- β), and interleukin (IL)-10 secreted from cancer cells, further decreasing the function of anti-cancer immunity." (PMID 35685630, 2022). "However, in cancer, hypoxia seems to enhance the IL-10 production by B cells." (PMID 35565420, 2022).
cancer (continued). "Various inflammatory biomarkers have been discussed in cancer studies as they have been linked to advanced cancer stages, resistance to immunotherapy, and poor prognosis: tumor necrosis factorα (TNF-α), interferon-γ (IFN-γ), and interleukin (IL)-1, IL-6, IL-8, IL-10, IL-11, and IL-17." (PMID 36499628, 2022). "However, as reviewed in 2019, IL-10 showed conflicting effects on immunity and cancer." (PMID 36212143, 2022). "In addition, significant enrichment of immunosuppressive cytokines TGFB1 and IL10 have been found in the Epithelial-mesenchymal transition-high group of almost all cancer types, forming an immunosuppressive microenvironment and leading to decreased infiltration of CD8+ T cells." (PMID 36703779, 2022). "Therefore, our data reflect multiple aspects observed in clinical studies and may partially explain why some cancer patients respond to PEGylated IL-10 treatment or IL-10 in combination with anti-PD-1 immunotherapy, while others do not." (PMID 34769278, 2021). "IL-10 has been recognized as one of the most important immunosuppressive cytokines, and accumulating evidence suggests that it has pleiotropic effects on immunoregulation and inflammation, as well as being one of the most critical modulators in anti-cancer immune responses." (PMID 34769278, 2021). "Therefore, increased levels of IL-10 by U937 cells in the presence of carnosine may suggest an anti-cancer mechanism." (PMID 33809496, 2021). "Thus, my findings suggest that IL-10 is a potential candidate for cancer immunotherapy." (PMID 33912464, 2021). "Intriguingly, MDSCs are also implicated in MET in cancer cells and during the formation of premetastatic niches; MDSCs reach the niche before the cancer cells and promote their seeding by secreting immunosuppressive factors, including S100A8/A9, FGF-β, IL-10, and IL-4." (PMID 34576042, 2021). "The production of IL-10 in mouse B cells could be enhanced by up to 60-fold for some preparations, while the antibody-mediated cytotoxicity of natural killer (NK) cells against cancer cells could be enhanced through IL-12-dependent and independent mechanisms." (PMID 32466253, 2020). "In the meantime, DCs also have the potential to induce T cell anergy and develop a cancer-promoting local microenvironment through expressing immune checkpoint molecules and releasing anti-inflammatory cytokines like transforming growth factor β (TGFβ) and interleukin 10 (IL10)." (PMID 33228747, 2020). "Additionally, the expression level of IL-10 is positively correlated with cancer recurrence." (PMID 32547401, 2020). "Our stable IL-10 protein could be a potential building block for generating a potent and more effective and selective IL-10-based immunotherapy for treating inflammatory diseases and cancers." (PMID 32849644, 2020). "The presence of IL12, however, induced also IL10 secretion in CAR T cells that may have double impact on an immune attack against cancer cells: antigen presentation of APC may be inhibited but on the other hand IL10 will modify cancer promoting chronic inflammation." (PMID 32260097, 2020). "Importantly, preclinical, and clinical data suggest that a signaling axis consisting of complement/C3aR/C5aR/IL-10 critically regulates T cell mediated antitumor immunity and manipulation of the pathway ex vivo and in vivo is an effective strategy for cancer immunotherapy." (PMID 31379815, 2019). "Indeed, cancer cells are reported to be able to recruit anti-inflammatory cells like Treg lymphocytes and myeloid-derived suppressor cells or secrete soluble immunosuppressive factors like TGFβ, IL-10, or PD-L1." (PMID 31687031, 2019). "Hence, the observations here that IL-15C-drives STAT3 activation in NK cells and their production of IL-10 may indicate that targeting of NK cells in this context could reduce the efficacy of anti-cancer IL-15C therapy or at least limit NK cell cytotoxicity." (PMID 31552035, 2019).
cancer (continued). "Additionally, oxidation products generated by TAMs contribute to cancer cell genetic instability, and IL-10 and TGFβ promote the immunosuppressive activity of Treg cells and in general have immunosuppressive effects via prostaglandin production, supporting tumor progression." (PMID 31554173, 2019). "Furthermore, a combination of treatment strategies targeting the complement/C3aR/C5aR/IL-10 pathway with other treatment modalities may improve cancer therapeutic efficacy." (PMID 31379815, 2019). "Hence, it could be suggested that NDV + tamoxifen exhibited a synergistic effect, which prevents cancer growth through suppression of IL-10 secretion." (PMID 30947706, 2019). "In contrast, IL-10 may rather manifest itself as a pro-inflammatory factor in cancer patients." (PMID 31340751, 2019). "However, as lesion progression advanced toward cancer, production of these pro-inflammatory mediators declined and, instead, there was an increase in inhibitory Treg and in production of the inhibitory mediator IL-10." (PMID 29664967, 2018). "However, the mechanism of IL10 upregulation is not well understood, and it remains unclear whether cancer cells secrete IL10 and whether IL10 has an impact on the aggressiveness and malignancy of cancer cells." (PMID 26956044, 2016). "Therefore, IL10 overexpression in M2 macrophages may protect cancer cells from lysis by immune cells." (PMID 26956044, 2016). "Nevertheless, it was suggested that one specific cytokine pattern may have a prognostic effect, since high interleukin 6 or interleukin 10 serum concentrations are associated with negative prognoses in independent types of cancer." (PMID 26905729, 2016). "Interestingly, IL-10-producing IgA+ plasmocytes were also identified in therapy-resistant and metastatic human PC, highlighting the potent immunosuppressive functions of this subset in cancer." (PMID 26071023, 2015). "Considering the ability of a broad-MMP inhibitor to decrease cancer cell invasion and cancer cell-induced angiogenesis, we hypothesized that the distinct ability of LPS- and IL-10-stimulated macrophages in inducing these cancer cell activities could be associated to proteolytic differences." (PMID 26043921, 2015). "Likewise as with IL-10, caution is needed when evaluating anti-IL-35 treatments for cancer." (PMID 25682197, 2015). "We continued to examine whether the Chinese medicine XAT might affect the activity of the proinflammatory cytokines IL-1β and TNF-α, which are important in the development of inflammation and cancer pain, as well as the anti-inflammatory cytokine IL-10, which may inhibit inflammation and pain." (PMID 26617438, 2015). "Thus, IFN-γ and anti-inflammatory cytokine IL-10 protect the host against cancer." (PMID 24670367, 2014). "IL-10 deficiency increases IL-1 levels, promoting cancer in the absence of IL-10." (PMID 24670367, 2014). "Thus, the inhibition of IL-10 has been proposed as a useful strategy in anti-cancer therapy." (PMID 23663506, 2013). "Furthermore, cancer cells themselves may also secrete factors such as IL-10 that lower DC survival by suppressing the anti-apoptotic genes Bcl-2, Bcl-XL, and Bfl-1." (PMID 23870437, 2013). "In the subgroup analysis by ethnicity, we found an evidence for the association between the IL-10-592C>A polymorphism and cancer risk among Asians but not among Europeans or Africans, suggesting a possible role of ethnic differences in genetic backgrounds and the environment they lived in." (PMID 23460834, 2013). "Haploblock analysis of the four genotyped Interleukin 10 (IL-10) SNPs revealed that one SNP (rs1800896) was negatively associated with oral SCCA, while two other SNPs, rs1800871 and rs1800872, were positively associated with the risk of having a diagnosis of oral precancer or cancer." (PMID 24278120, 2013). "Interestingly, this broaches the possibility that IL-10-derived from such Th cells may act, in part, as an immunological adjuvant in the antitumor response to cancer." (PMID 23533029, 2013).